TNF (tumor necrosis factor)
Diseases named in the same sentence as TNF in open-access papers (continued):
Sharing a sentence is not in itself a finding about the gene and the disease.
Insulin resistance (continued). "Apocynin administration suppressed the expression of these inflammatory agents, resulting in the reduction of circulating TNF-α, IL-6, and leptin levels that normally accompany insulin resistance." (PMID 21403905, 2010). "A possibility is therefore that cytokines, such as interleukin (IL)-6 and tumor necrosis factor (TNF)-α, contribute to the development of insulin resistance and impaired islet function." (PMID 20529356, 2010). "Numerous studies have demonstrated that TNF-α limits insulin receptor signaling and promotes insulin resistance." (PMID 20808947, 2010). "Experimental studies indicate that insulin resistance occurring in HCV core-transgenic mice is due at least partly to an increase in TNF-α secretion." (PMID 21994721, 2010). "The molecular pathways that link inflammation and insulin resistance include a variety of cytokines and adipocytokines such as TNF-α, IL-6, MCP-1, leptin, and adiponectin." (PMID 21403905, 2010). "The magnitude of induction of the intestinal inflammatory biomarker, TNF-α, strongly correlates with HF-diet induced weight gain, adiposity and insulin resistance in CONV animals with intact commensal microbiota." (PMID 20808947, 2010). "The activation of inflammation by the UPR also depends upon the IKK-NFκB pathway, also through IRE-1α, resulting in increased TNF-α and IL-6 production, further supporting its contribution to insulin resistance." (PMID 20706689, 2010). "Inflammatory cytokines like TNFα, can act as mediators of insulin resistance by impairing the tyrosine kinase activity of both the insulin receptor (IR) and insulin receptor substrate (IRS-1), thus inhibiting insulin signaling." (PMID 20634940, 2010). "Reducing TNF-α signaling either by TNF-α knocking out mechanisms or by infusion of blocking antibodies reduces insulin resistance in obese rodents." (PMID 20426802, 2010). "The exact role of the opposite effects and clinical impact of p-TNF-α and p-IL-6 on development of insulin resistance and perhaps type 2 diabetes in subjects with unintentional wasting and women who gained body weight now needs to be examined further." (PMID 20529356, 2010). "TNF-α and IL-6 are known to promote lipolysis and the secretion of free fatty acids, which contributes to an increase in hepatic glucose production and insulin resistance." (PMID 20825686, 2010). "In obese subjects, infiltrated macrophages together with enlarged adipocytes secrete numerous pro-inflammatory mediators such as IL-6 and TNF-α, which contribute to insulin resistance." (PMID 20735814, 2010). "A previous study demonstrated that age, intramyocellular lipid, and TNF-α are the strongest predictors of insulin resistance." (PMID 20877574, 2010). "Mediators of systemic inflammatory response, such as interleukin-1 (IL-1) and tumor necrosis factor alpha (TNF-α), cause hyperglycaemia and peripheral insulin resistance by inducing the release of stress hormones." (PMID 20615210, 2010). "Our study extends this observation further and suggests that adipose tissue inflammation reflected by increases in CD68 and TNF-α expressions plays an important role in the whole-body insulin resistance in patients with COPD." (PMID 21197447, 2010). "Recently, it was demonstrated that siRNA-mediated reduction of IKKβ prevented TNFα-induced insulin resistance in human skeletal muscle ex vivo, possibly reducing insulin resistance." (PMID 19519361, 2009). "TNF-α is also produced by adipose tissue and it is thought to play a major role in the Metabolic Syndrome (MS), which is characterized by insulin resistance and inflammation." (PMID 19558671, 2009). "There are other factors causing insulin resistance, known to be involved in elevated IRS-1 serine phosphorylation including tumor necrosis factor α (TNF-α), free fatty acids, cellular stress, amino acids, and insulin." (PMID 19169352, 2009).
Insulin resistance (continued). "Adipose tissue has been shown to produce tumor necrosis factor-alpha, which has the ability to reduce insulin secretion and induce insulin resistance." (PMID 19558671, 2009). "Serum TNF-α concentration has been reported to be positively correlated with systolic blood pressure and insulin resistance in humans, and increased TNF-α secretion has been observed in monocytes from hypertensive patients." (PMID 18416854, 2008). "MAP4K4 expression is induced by TNF-alpha and promotes insulin resistance, whereas silencing of MAP4K4 prevents insulin resistance in human skeletal muscle and enhances glucose uptake." (PMID 18671879, 2008). "Question 2: Do variations in genes encoding the NF-kappa B, the TNF-α and the JNK, independently or in synergy, predict an enhanced inflammatory response and subsequent insulin resistance in Dahl S rats in excessive salt environment?" (PMID 18570670, 2008). "Although TNFα has been found to be a mediator of insulin resistance in acute and chronic models of inflammation, TNFα was not identified as an influential mediator in our model." (PMID 19087258, 2008). "Some investigations have demonstrated that reactive oxygen species (ROS) production increases during insulin resistance and then triggers lipid peroxidation, mitochondrial dysfunction and releasing of several cytokines, such as tumor necrosis factor-α (TNF-α)." (PMID 18822121, 2008). "Inaddition, evidence for a direct role of TNF-α in insulin resistance inhumans in vivo has been obtained." (PMID 19148295, 2008). "Map4k4 gene silencing in human skeletal muscle prevents tumor necrosis factor-alpha-induced insulin resistance." (PMID 18570670, 2008). "They suffer from a chronic state of insulin resistance, with inhibition of the insulin-signaling cascade by free fatty acids or by inflammatory cytokines, such as TNFα." (PMID 19055829, 2008). "Increased plasma levels of TNF-α have been observed in subjects with insulin resistance as well as in patients with early onset of coronary heart disease." (PMID 23675033, 2007). "Tumor necrosis factor (TNF)-α is cytokine secreted byadipose tissue that plays an important role in insulin resistance." (PMID 17389770, 2007). "Firstly, it is known that TNF-α expression is increased in patients with weight gain and insulin resistance." (PMID 16669999, 2006). "Recent results from the INCHIANTI population study showed that subjects in the upper tertile of insulin resistance had increased serum levels of TNF-α, IL-1R antagonist and IL-6 and low levels of sIL-6R." (PMID 15904534, 2005). "Patients with type 2 diabetes and insulin resistance, many of whom are obese, have elevated levels of several inflammatory markers, including IL-6, TNFα, and sTNFR2." (PMID 15578112, 2004). "In the T2D model, TH mice exhibited more severe hyperglycemia, insulin resistance, and β‐cell dysfunction than TN mice, accompanied by increased hepatic TNF‐α and IL‐6 expression, enhanced lipid accumulation, suppressed IRS‐1 phosphorylation, and enhanced JNK and IKKβ phosphorylation." (PMID 41388732, 2026). "Pathway enrichment analysis linked CK18 elevation to processes involved in NAFLD pathogenesis, including insulin resistance, TNF‐α‐mediated inflammation, and apoptosis, which supported the biological plausibility of CK18 participation in systemic metabolic and inflammatory pathways." (PMID 41551909, 2026). "Subcutaneous adipocytes were hypertrophic, and flow cytometry identified increased TNFα‐positive macrophages, an inflammatory milieu that could promote insulin resistance." (PMID 41622197, 2026). "A chronic excess body weight condition increases production of free fatty acids, cytokines such as TNF-α and IL-6, and leptin from adipose tissue, whereas it decreases adiponectin production, which together lead to the development of insulin resistance and chronic hyperinsulinemia." (PMID 41376649, 2026).
Insulin resistance (continued). "Enhancements in inflammatory and metabolic indicators, such as decreased TNF-α, IL-6, and insulin resistance, may facilitate ideal endometrial gene expression profiles associated with implantation, including integrins, HOXA10, IGFBP-1, and angiogenic pathways." (PMID 41596408, 2026). "Studies have demonstrated that berberine enhances lipid metabolism, lowers LDL-C, TG, and TC levels, improves insulin resistance and oxidative stress, and exerts anti-inflammatory effects through the inhibition of TNF-α and IL-6 secretion, as well as modulation of the PPARγ signaling pathway." (PMID 41304686, 2025). "Even in eutrophic adolescents, but with a high %BF, IL-6 was correlated with other inflammatory cytokines, such as TNF-α and with the development of insulin resistance as well as, with modulating the synthesis of CRP, showing the role of adipose tissue in inflammation." (PMID 40717997, 2025). "Adipokines such as leptin and TNF-α, secreted from adipose tissue, may further aggravate insulin resistance and impair β-cell function." (PMID 41036138, 2025). "Additionally, Ang 1–7 decreased MCP-1 secretion in hypertrophic adipocytes and TNF-α-treated adipocytes, which is a model of insulin resistance." (PMID 39803918, 2025). "Although this effect is beneficial to local renal tissues, further research is needed to see whether the decrease in TNF-α and IL-6 reduces insulin resistance." (PMID 40872492, 2025). "Since NF-κB and TNF are involved in the induction of insulin resistance, and curcumin can modulate NF-κB activity and TNF expression, curcumin may be effective in reducing the incidence of type II diabetes." (PMID 40718452, 2025). "Furthermore, in TNF-α-induced insulin resistance, adipocytes exhibit the decreased sialylation of membrane glycoproteins, which correlates with reduced GLUT4 translocation to the plasma membrane and impaired glucose uptake." (PMID 41301440, 2025). "The major mechanisms of insulin resistance in CKD are thought to involve pro-inflammatory cytokines such as tumor necrosis factor-α (TNF-α), interleukin-6 (IL-6), and interferon-γ (IFN-γ), which inhibit phosphorylation of the insulin receptor and insulin receptor substrate-1 (IRS-1)." (PMID 41157262, 2025). "The pathophysiology of MetS is strongly linked to adipokine dysregulation, where excessive adipose tissue secretes pro-inflammatory cytokines such as tumour necrosis factor alpha (TNF-alpha) and interleukin-6 (IL-6), exacerbating insulin resistance and hypertension." (PMID 40539174, 2025). "Moreover, hyperglycemia and insulin resistance stimulate systemic inflammation by the release of pro-inflammatory cytokines such as interleukin-6 (IL-6) and tumor necrosis factor-alpha (TNF-α) aggravating vascular damage." (PMID 40114220, 2025). "Notably, TNF-α inhibits insulin receptors, impairing the glucose uptake in peripheral tissues, while IL-6 contributes to insulin resistance by reducing adiponectin levels." (PMID 41284085, 2025). "Similarly, kaempferol modulates the AGE–RAGE signaling pathway, forms stable hydrogen bonds with the inflammatory target CXCR1, suppresses TNF-α release, and alleviates insulin resistance." (PMID 41155161, 2025). "Tnf is a tumor necrosis factor and it has been demonstrated that short exposures to PM2.5 significantly increase liver inflammatory factors including Il-6 and Tnf-α in rats, while the activation of inflammatory factors has been shown to contribute to insulin resistance." (PMID 40863931, 2025). "Mechanistically, it promotes inflammation via IL-6, TNF-α, and IL-1β and may contribute to insulin resistance." (PMID 41464844, 2025). "Moreover, silymarin supplementation improves insulin resistance and reduces hepatic levels of inflammatory cytokines TNF-α and IL-6." (PMID 39858534, 2025). "Furthermore, elevated serum TNF activity has been observed in dairy cows affected with a naturally occurring fatty liver and is correlated with insulin resistance." (PMID 40869340, 2025).
Insulin resistance (continued). "Several investigations have indicated a notable decrease in serum lipid profiles, fasting glucose levels, insulin resistance, insulin, HbA1c, interleukin‐6, TNF‐α, CRP, and liver enzymes aspartate aminotransferase, alanine transaminase after consumption of propolis and increase HDL‐C." (PMID 41245948, 2025). "Insulin resistance reduces nitric oxide (NO) bioavailability, promoting vasoconstriction and vascular stiffness, while also enhancing the production of pro-inflammatory cytokines, including TNF-α and IL-6, further accelerating vascular damage." (PMID 40839683, 2025). "Reduced blood pressures, fasting serum glucose, insulin levels, insulin resistance, Serum tumor necrosis factor α, C-reactive protein, the total and low-density lipoprotein cholesterol, and triglycerides; increased total antioxidant status and high-density lipoprotein cholesterol." (PMID 39857788, 2025). "Increased gut permeability, promoted neutrophil infiltration, and increased levels of IL-6, IL-1β, and TNF-α, and increased skeletal muscle insulin resistance and inflammation via simulating PPAR-δ are some suggested mechanisms attributed to simple sugar intake." (PMID 39974842, 2025). "In addition, TNF-α, one of the first proinflammatory cytokines secreted in sepsis, has been shown to promote insulin resistance." (PMID 39838305, 2025). "Moreover, exercise-induced secretion of interleukin-6 (IL-6) from muscle cells has anti-inflammatory effects by inhibiting cytokines like tumor necrosis factor alpha (TNF-α) and interleukin-1 beta (IL-1β), contributing to reduced insulin resistance." (PMID 41008394, 2025). "Furthermore, more studies on other insulin in vitro insulin resistance models, including chronic high-insulin- or TNF-a-exposed cell models, are necessary to provide consolidated understanding." (PMID 41155560, 2025). "Interestingly, O-TFSE retained similar efficacy in reversing TNF-α-induced insulin resistance and demonstrated significantly stronger α-glucosidase and α-amylase inhibitory activities, indicating its enhanced potential for diabetes management." (PMID 40807540, 2025). "The immune system’s pro-inflammatory environment in IBD, characterized by cytokine dysregulation (e.g., TNF-α, IL-6, IL-1β), may contribute to systemic inflammation, further exacerbating insulin resistance in older individuals." (PMID 41007787, 2025). "For instance, the presence of inflammatory cytokines such as interleukin-6 and tumor necrosis factor-alpha has been positively correlated with metabolic disturbances, including insulin resistance and dyslipidemia, which are critical factors in the pathogenesis of cardiovascular diseases." (PMID 40408377, 2025). "IL-6 levels were strongly associated with hypertriglyceridemia (OR = 1.096, 95% CI: 1.044–1.151, p < 0.001) and insulin resistance (OR = 1.068, 95% CI: 1.030–1.107, p < 0.001), while TNF-α correlated with abdominal obesity (WHtR OR = 1.429, 95% CI: 1.005–2.031, p = 0.047)." (PMID 40137151, 2025). "Elevated TNF-α concentrations might play a role in the inflammatory environment that worsens insulin resistance and disrupts glucose metabolism." (PMID 40002771, 2025). "Moreover, TNF-α has been identified as a crucial factor in disrupting the insulin signaling system and promoting insulin resistance." (PMID 40541990, 2025). "The pro-inflammatory cytokine environment in IBD, involving molecules like TNF-α, IL-6, and IL-1β, appears to exacerbate insulin resistance, especially in older individuals who may already be more vulnerable to metabolic disturbances." (PMID 41007787, 2025). "Additionally, TNF‐alpha reduces adiponectin secretion, a hormone that improves insulin sensitivity, further contributing to insulin resistance." (PMID 40551726, 2025). "In addition, reduced systemic levels of pro-inflammatory cytokines and mediators such as TNF-α and C-reactive protein lead to improvements in insulin resistance and insulin signaling." (PMID 40299548, 2025).
Insulin resistance (continued). "TNF-α interferes with insulin signaling promoting insulin resistance." (PMID 40567989, 2025). "It has been proposed that TNF- α, not IL-6, is the primary cause of insulin resistance and dyslipidemia and that IL-6 is its marker." (PMID 39817379, 2025). "At higher WWI values, increased visceral fat may trigger early insulin resistance, endothelial dysfunction, and elevated pro-inflammatory cytokines (e.g., TNF-α, IL-6), exacerbating renal microvascular injury and protein leakage." (PMID 40700436, 2025). "TNF-α is a well-known cytokine that induces insulin resistance." (PMID 40286055, 2025). "Psoriasis and metabolic syndrome may exacerbate each other—adipose tissue inflammation and insulin resistance can worsen psoriasis, and psoriasis-related cytokines (like TNF-α and IL-6) can induce insulin resistance and dyslipidemia, creating a vicious cycle." (PMID 41112228, 2025). "Additionally, TNF-α and IL-6 contribute to hepatic insulin resistance through upregulation of Suppressor of Cytokine Signaling 3 (SOCS3)." (PMID 41472723, 2025). "Adipose tissue exosomes can also modulate macrophage activation and the production of proinflammatory cytokines such as IL-6 and TNF-α via increased obese adipose exosomal miR-34a’s, which inhibits M2 polarization and positively correlates with insulin resistance." (PMID 40696355, 2025). "The increased levels of pro-inflammatory cytokine TNF-α found here in rotenone-treated rats secreted by Th1 cells could be related to inflammation and insulin resistance." (PMID 39851552, 2025). "On the other hand, TNF-α and IL-6 act as pro-inflammatory factors that increase insulin resistance." (PMID 40260393, 2025). "VAT functions as an endocrine organ, releasing proinflammatory cytokines (e.g., TNF-α and IL-6) and free fatty acids that mechanistically contribute to insulin resistance and oxidative stress through dysregulation of glucose homeostasis and mitochondrial dysfunction." (PMID 40702394, 2025). "In fact, it was shown that the pro-inflammatory cytokines IL-6, MCP-1, IL-1β, and TNF-α secreted by hypertrophic adipose tissue in obese individuals can disrupt insulin signalling and promote insulin resistance, contributing to the pathophysiology of diabesity." (PMID 41155431, 2025). "Chronic low-grade inflammation, characterized by persistent elevation of pro-inflammatory cytokines (e.g., IL-6, TNF-α), and metabolic syndrome components, including insulin resistance, hypertension, and dyslipidemia, have been identified as shared risk factors for both conditions." (PMID 40356818, 2025). "TNF-alpha and IL-6 indirectly mediate lipolysis and increase hepatic fatty acid synthesis, and they are positively related to adiposity and are correlated with cardiovascular disease (CVD) risk factors and insulin resistance." (PMID 41441034, 2025). "Insulin resistance may trigger the release of inflammatory mediators such as tumor necrosis factor-alpha and interleukin-6, potentially compromising airway structural integrity and disrupting central nervous system functions." (PMID 40078414, 2025). "These stressors activate key inflammatory pathways such as Nuclear Factor kappa-light-chain-enhancer of activated B cells (NF-κB) in the liver, promoting the production of pro-inflammatory cytokines like IL-6, IL-1β, and TNF-α, which together foster insulin resistance and low-grade inflammation." (PMID 40564033, 2025). "Under conditions of insulin resistance, the secretion of pro-inflammatory cytokines, such as TNF-α and IL-6, is elevated, which may worsen chronic intestinal inflammation." (PMID 40936909, 2025). "Possible explanations include that skeletal muscle has been shown to regulate interleukin-6, tumor necrosis factor-alpha, and insulin resistance, and reduced muscle mass may result in a pro-inflammatory state that can dampen the host immune response to cancer." (PMID 39831184, 2025).